ALK (ALK receptor tyrosine kinase)
Diseases named in the same sentence as ALK in open-access papers (continued):
Sharing a sentence is not in itself a finding about the gene and the disease.
lung adenocarcinoma (continued). "We evaluated 6 ALK-positive lung adenocarcinoma patients who tested Ventana IHC-positive and FISH-negative and assessed their clinical responses to the ALK tyrosine kinase inhibitor (TKI) crizotinib." (PMID 27418132, 2016). "In this study, we evaluated 6 lung adenocarcinoma patients with FISH-negative and Ventana IHC-positive ALK results, 3 of whom were validated with RT-PCR technology, including 2 who were also validated with NGS and RNAscope ISH methods." (PMID 27418132, 2016). "Current international guidelines recommend analysis of the following seven genes before starting palliative intent therapy for lung adenocarcinoma: KRAS, EGFR, ALK, ROS1, HER2, BRAF, RET." (PMID 26018876, 2015). "Relationship between ALK status and clinic, EGFR characteristics in the unselected 368 lung adenocarcinomas." (PMID 24667320, 2014). "Using the newly developed antibody, ALK (D5F3), we analyzed ALK expression in 297 lung adenocarcinoma cases." (PMID 24422905, 2014). "Here, we review advances in targeted treatment of lung adenocarcinoma with respect to five clinically relevant biomarkers – EGFR, ALK, MET, ROS-1, and KRAS." (PMID 25157335, 2014). "The discovery of driver mutations, such as epidermal growth factor receptor (EGFR) and anaplastic lymphoma kinase (ALK), has led to remarkable improvements in personalized therapies for lung adenocarcinoma." (PMID 24576404, 2014). "The majority of Caucasian lung adenocarcinoma harboring EML4-ALK show the signet-ring cell histology, whereas the acinar pattern is pre-dominant in ALK-positive Asian adenocarcinomas." (PMID 27234388, 2013). "TTF-1, CK7, and Napsin A positivity on IHC confirmed lung adenocarcinoma, a disease increasingly seen in non-smokers due to factors such as genetic mutations (e.g., EGFR, ALK) and environmental exposures." (PMID 40821205, 2025). "Compared to EGFR mutations, which are more commonly observed in elderly patients, ALK rearrangements are predominantly found in younger patients (<60 years old), non-smokers, or light smokers with lung adenocarcinoma." (PMID 41020204, 2025). "Other alterations, such as ALK rearrangements and BRAF mutations, also appear more frequently in radon-exposed populations and are frequently observed in non-smoking lung adenocarcinomas." (PMID 40823246, 2025). "It usually occurs in light or non-smokers with lung adenocarcinoma, and the most frequent fusion is the echinoderm microtubule-associated protein-like 4 gene (EML4)-ALK variant." (PMID 40297141, 2025). "All lung adenocarcinoma samples, ALK positive and negative cell control showed a standard staining pattern when the antibody dilution rate was 1:200 (Figures 7A2–C2)." (PMID 40017673, 2025). "This case demonstrates the potential efficacy of neoadjuvant alectinib in managing stage III ALK-mutant lung adenocarcinoma, particularly when traditional chemoimmunotherapy is not well-tolerated." (PMID 41293380, 2025). "We also analyzed the relationship between RacGAP1 expression and common lung adenocarcinoma driver gene state (mutated and non-mutated), in particular EGFR, ALK and K-RAS, finding no obvious and significant difference." (PMID 40497948, 2025). "ALK-positive patients are typically younger and have a history of never or light smoking compared to those with ALK-negative lung adenocarcinoma." (PMID 39497711, 2024). "Patients with lung adenocarcinoma who have never smoked (NSLA) and lack key driver mutations, such as those in the EGFR and ALK genes, face limited options for targeted therapies." (PMID 39300154, 2024). "IMA has a higher rate of ALK rearrangement mutations (2.2%) and a lower rate of EGFR mutations (0–5%) than nonmucinous adenocarcinoma of the lung." (PMID 38303008, 2024). "The SPECC1L::ALK fusion was first mentioned in a Chinese patient with lung adenocarcinoma in 2019, but no details about the clinical outcome of the patient were reported." (PMID 39063924, 2024).
lung adenocarcinoma (continued). "For patients with treatment-naïve advanced lung adenocarcinoma, the ALK test should be performed irrespective of smoking status and age." (PMID 37007097, 2023). "Patient#A was a 69-year-old male, former smoker, treated for a lung adenocarcinoma TTF1+ without EGFR, KRAS, or BRAF mutation or ALK or ROS1 translocation but an expression of 100% of PDL1 on the tumor cell." (PMID 37370798, 2023). "Despite the proportion of tumors harboring EGFR, ALK, or KRAS alterations being consistent with the frequency reported in lung adenocarcinoma, the reduced subgroup size, especially for ALK-positive cases, might have limited the strength of the models." (PMID 37760521, 2023). "Patient#B was a 53-year-old male, current smoker, with a lung adenocarcinoma TTF1+ PDL1 0% without EGFR, KRAS, or BRAF mutation or ALK and ROS1 translocation but STK11 mutation." (PMID 37370798, 2023). "This is the first reported case of a 74-year-old female with stage IV lung adenocarcinoma, featuring a novel Kinesin Family Member 13A (KIF13A)-ALK fusion, identified via next-generation sequencing (NGS) and confirmed with fluorescence in situ hybridization (FISH)." (PMID 38155713, 2023). "The gene fusions, identified by ADx in samples lacking FISH confirmation (sample 41–52), were in line with the patient’s diagnosis: KIAA1549-BRAF in astrocytoma, ALK or NTRK translocations in thyroid papillary carcinoma, lung adenocarcinoma as well as sarcomas NOS." (PMID 36338518, 2022). "Herein, we described a case of lung adenocarcinoma carrying ALK-HLA-DRB1 fusion in a 48-year-old nonsmoking woman." (PMID 35280798, 2022). "All ERBB2 mutated patients were diagnosed with lung adenocarcinoma, were never smokers, and wild‐type for EGFR, KRAS, and ALK hotspot alterations." (PMID 36251951, 2022). "Compared with ALK, EGFR, and TTF1, UCHL1 has higher predictive accuracy for lung adenocarcinoma." (PMID 35546675, 2022). "Our report suggests that crizotinib can be extremely effective in ALK‐positive lung adenocarcinoma without CNS involvement as a first line treatment in AYA patients." (PMID 35092185, 2022). "This was significantly higher than that observed in lung adenocarcinomas with an EGFR mutation, with a KRAS mutation but lacking an ALK mutation, or with either an EGFR or KRAS mutation (all P < .005)." (PMID 35984185, 2022). "ALK, EGFR, and TTF1 are commonly used to detect lung adenocarcinoma." (PMID 35546675, 2022). "ALK gene rearrangements in lung adenocarcinoma were more commonly seen in non-smokers (31.25%) as compared to smokers (6.25%)." (PMID 34514573, 2022). "Histological transformation of lung adenocarcinoma into SCLC is a rare event, which has been described as a key resistance mechanism to tyrosine kinase inhibitor (TKI) treatment in around 5% EGFR-mutant and few ALK-rearranged NSCLC cases." (PMID 35511434, 2022). "ALK gene rearrangements in lung adenocarcinoma are more commonly seen in females, non-smokers and in patients having pleural effusions." (PMID 34514573, 2022). "Patients with lung adenocarcinoma with CNS metastases, without activating EGFR mutation and without ALK rearrangement, benefit from immunotherapy." (PMID 33435596, 2021). "ALK-rearranged lung adenocarcinomas most often affect middle-aged patients and light or non-smokers." (PMID 33237469, 2021). "Our study followed up and reviewed the prognosis and clinical characteristics of 80 ALK rearranged lung adenocarcinoma patients and 3031 ALK‐negative patients." (PMID 34596344, 2021). "A large proportion (∼5 percent) of lung adenocarcinoma patients as well as breast and colorectal tumors are found in pathological fusion sections of this gene with portions of ALK gene that produces the EML4-ALK transcript." (PMID 33986802, 2021). "EGFR, ALK, and KRAS were common driver gene in Chinese patients with stage IV lung adenocarcinoma." (PMID 33997043, 2021).
lung adenocarcinoma (continued). "Studies in the past decade have reported that tyrosine kinase inhibitors (TKIs) targeting epidermal growth factor receptor (EGFR), anaplastic lymphoma kinase (ALK), and ROS proto-oncogene 1 (ROS1) are potential therapeutic targets for lung adenocarcinoma, upon genotyping." (PMID 33072571, 2020). "In addition, multiple gene fusions, such as NRG1, RET, and ALK, were only detected in IMA patients in our cohort and the detecting rate (16/51, 31.4%) of gene fusions was significantly higher than the unselected lung adenocarcinoma patients." (PMID 33505917, 2020). "In the present study, both ALK-translocated and ALK-negative lung adenocarcinoma specimens in tissue sections were collected for immunohistochemistry." (PMID 32164629, 2020). "We report a case of EGFR wild-type and ALK-negative lung adenocarcinoma patient with multiple symptomatic BMs, who received apatinib together with brain radiation therapy." (PMID 32351894, 2020). "In the past decade, studies have identified tyrosine kinase inhibitors (TKIs) targeting epidermal growth factor receptor (EGFR), anaplastic lymphoma kinase (ALK), and ROS proto-oncogene 1 (ROS1) as potential therapies for lung adenocarcinoma on the basis of genotyping." (PMID 32607285, 2020). "In our study, we performed on the patients with stage IV lung adenocarcinoma in our region and found preoperative serum levels of SCCAg, CYRF21‐1, and NSE not suitable for the detection of ALK mutation." (PMID 31489711, 2020). "Both ALK-translocated and ALK-negative lung adenocarcinoma specimens in tissue sections were collected for immunohistochemistry." (PMID 32164629, 2020). "Using the ALK-positive and ALK-negative lung adenocarcinoma specimens collected from Beijing Xuanwu Hospital, we analysed the expression of NHERF1 by immunohistochemistry on tissue sections." (PMID 32164629, 2020). "Through this study, prognostic meaningful lung adenocarcinoma subtypes which are independent of EGFR and ALK mutations and the relevant mutational and expressional profiles were identified." (PMID 31987030, 2020). "We found that the NHERF1 staining was much more intensive in samples of ALK-translocated tissues, compared to that in ALK-negative lung adenocarcinoma tissues." (PMID 32164629, 2020). "This study confirmed that ALK-rearrangement is more common in non-smoking patients suffering from lung adenocarcinoma." (PMID 30744199, 2019). "195/469 (41.6%) patients had triple-negative (EGFR-negative/KRAS-negative/ALK-negative) lung adenocarcinomas." (PMID 30744664, 2019). "ROS1 rearrangement with an incidence of 4% of lung adenocarcinoma which are EGFR and ALK negative represents an important targetable driver mutation in the Indian population." (PMID 30915158, 2019). "The analysis revealed strong evidence of an increased prevalence of ALK gene rearrangement in the non-smoking population, as compared to the general population of lung adenocarcinoma patients." (PMID 30744199, 2019). "The influence of ALK rearrangements on metabolism has not been well described in lung adenocarcinoma." (PMID 31795465, 2019). "This study was aimed at investigating the prognostic significance of Baculoviral IAP repeat containing 5 (BIRC5) in lung adenocarcinoma (LAD) lacking EGFR, KRAS, and ALK mutations (triple-negative (TN) adenocarcinomas)." (PMID 31093306, 2019). "were detected in 11% of patients with advanced non-squamous NSCLC and in 13% of patients with lung adenocarcinoma, while 12% of patients with non-squamous NSCLC and 10% of patients with lung adenocarcinoma harbored ALK rearrangements." (PMID 30744664, 2019). "ROS1 rearrangement with an incidence of 4% of lung adenocarcinoma which is EGFR and ALK negative represents an important targetable driver mutation in the Indian population." (PMID 30915158, 2019).
lung adenocarcinoma (continued). "Rearrangement of the anaplastic lymphoma kinase (ALK) gene is an oncogenic driver event typically occurring in young non-smokers suffering from a KRAS/EGFR wild-type lung adenocarcinoma." (PMID 30326973, 2018). "Although the next generation ALK inhibitor alectinib (CH5424802) has shown efficacy in NSCLC, hypoxia was found to induce resistance to ALK inhibitors crizotinib and alectinib in lung adenocarcinoma by inducing an EMT phenotype." (PMID 30087852, 2018). "Unfortunately, EGFR mutations and ALK fusions are typically not present in LUSC28, and novel targeted agents for adenocarcinoma of the lung ineffective against LUSC." (PMID 30367091, 2018). "The development of targeted cancer therapies has led to improved results in the metastatic setting for patients with lung adenocarcinomas which bear oncogenic driver alterations, such as epidermal growth factor receptor (EGFR) and re-arranged anaplastic lymphoma kinase (ALK)." (PMID 30416904, 2018). "Unlike lung adenocarcinoma, activating mutations in EGFR and ALK fusion are typically not present in LSCC, so targeted agents are largely ineffective against LSCC." (PMID 29456509, 2018). "CBM have also been reported in cases of lung adenocarcinoma in which the ALK status was not evaluated." (PMID 29662531, 2018). "At the time of this study, analysis of ALK, ROS and MET mutations were not part of the standard of care in lung adenocarcinoma." (PMID 30064401, 2018). "The median PFS of ALK-positive lung adenocarcinoma was 7.1 months (95%CI: 6.1-8.1) and negative was 4.7 months (95%CI: 3.818-5.582), and the difference was statistically significant (χ2=13.269, P < 0.001)." (PMID 29167001, 2017). "ALK-positive lung adenocarcinoma patients with first-line pemetrexed-based chemotherapy have greater clinical benefit than ALK-negative patients." (PMID 29167001, 2017). "The aim of this study is to explore the efficacy of pemetrexed-based chemotherapy in patients with ALK-positive and negative lung adenocarcinoma." (PMID 29167001, 2017). "We found the ALK expression was homogenous in lung adenocarcinoma samples and there was no discordant case of ALK status between primary tumours and corresponding lymph node metastases." (PMID 28887531, 2017). "In this study, we selected 3 lung adenocarcinoma cell lines SPC-A1, SCH-1153 and A549, which were all inappropriate for TKIs due to the lack of EGFR mutations/ALK-fusions or possessing KRAS mutations." (PMID 29285248, 2017). "In this case report, we present a female patient initially diagnosed with ALK-negative lung adenocarcinoma that responded to standard chemotherapy, but was subsequently re-tested by NGS and found to be ALK-positive." (PMID 27480287, 2016). "ALK rearrangements were more often found in younger age patients, in never or light ex-smokers and in lung adenocarcinomas." (PMID 27386342, 2016). "The frequency of ALK rearrangements is approximately 5 % in lung adenocarcinomas and is higher in light or never-smokers and in younger individuals." (PMID 27655296, 2016). "A 74-year old female patient initially diagnosed with ALK-negative lung adenocarcinoma responded to initial standard chemotherapy." (PMID 27480287, 2016). "Currently, national guidelines and specialty societies support testing all lung adenocarcinomas for ALK aberrations, irrespective of other variables such as race, sex and smoking history." (PMID 26838801, 2016). "For example, ALK-translocation lung adenocarcinomas are characterized by young-onset, never/light smokers, and acinar morphology with mucin/signet-ring cell morphology." (PMID 27005669, 2016). "We performed amplification refractory mutation system (ARMS) fluorescence quantitative PCR to detect the gene status of EGFR, ALK, ROS1 and RET in resected samples from 280 patients who were confirmed to have primary lung adenocarcinomas with N1-N2 lymph node metastasis." (PMID 27563816, 2016).
lung adenocarcinoma (continued). "In a recent study of lung adenocarcinomas, mutation rates for EGFR (39%), KRAS (4%), ALK (15%), and HER2 (5%) in never-smoker groups differed from rates in current or former smoker groups (10%, 35%, 4%, and 1%, respectively)." (PMID 25760072, 2015). "Fusions of the tyrosine kinase genes ALK (anaplastic lymphoma kinase), ROS1 (c-ros oncogene 1), or RET (rearranged during transfection) occur in 1%–5% of lung adenocarcinomas (LADCs) and their products constitute therapeutic targets for kinase inhibitory drugs." (PMID 26437441, 2015). "Structure of breakpoint junctions for ALK, ROS1, and RET reciprocal fusions in lung adenocarcinoma." (PMID 26437441, 2015). "Because of the therapeutic significance of crizotinib, an ALK tyrosine kinase inhibitor, in ALK rearrangement cases, the differential diagnosis of MEC-like lesions from PMEC and other types of lung adenocarcinoma might be critical." (PMID 26575266, 2015). "Unlike lung adenocarcinoma, pulmonary LELC rarely presents with EGFR mutations, KRAS mutations or ALK rearrangements." (PMID 26361045, 2015). "However, several recent studies have demonstrated that a relatively new anti-ALK clone, D5F3, can identify ALK-rearranged lung adenocarcinoma more accurately than FISH." (PMID 25785456, 2015). "Patients with lung adenocarcinomas had a significantly higher rate of ALK rearrangements (7.2%) than patients with non-adenocarcinoma (2.0%) (OR = 2.25; 95% CI: 1.54–3.27; P<0.0001)." (PMID 24959902, 2014). "We analyzed whole exome sequencing data from 16 EGFR/KRAS/ALK-negative lung adenocarcinomas and additional 54 tumors in two expansion cohort sets." (PMID 24576404, 2014). "The genomic makeup of EGFR/KRAS/ALK-negative lung adenocarcinomas in never-smokers is remarkably diverse." (PMID 24576404, 2014). "Although genome-scale characterization of lung adenocarcinoma has been performed, a comprehensive somatic mutation analysis of EGFR/KRAS/ALK-negative lung adenocarcinoma in never-smokers has not been conducted." (PMID 24576404, 2014). "In conclusion, the ALK IHC using antibody D5F3 and DAKO Envision system as the initial screening followed by auxiliary FISH confirmation is a reliable, economical approach to identify ALK positive lung adenocarcinomas." (PMID 24667320, 2014). "We screened 230 surgically resected lung adenocarcinoma samples to identify EGFR/KRAS/ALK-negative tumors in never-smokers." (PMID 24576404, 2014). "In addition, epidermal growth factor receptor (EGFR) mutations and anaplastic lymphoma kinase (ALK) fusion genes have been identified in lung adenocarcinoma, and are considered as biomarkers for EGFR and ALK inhibitors." (PMID 25348872, 2014). "Because EML4-ALK fusion is not as frequent as EGFR gene mutation, it would be important to efficiently and accurately identify those lung adenocarcinomas that harbor ALK rearrangements in clinical practice to guide the appropriate therapy 9,10." (PMID 24403104, 2014). "Patients with lung adenocarcinomas had a significantly higher rate of ALK rearrangements (449/6200; 7.2%) than patients with non-adenocarcinoma (54/2724; 2.0%) (OR = 2.25; 95% CI: 1.54–3.27; P<0.0001; I2 = 26%)." (PMID 24959902, 2014). "We identified several targetable pathways in EGFR/KRAS/ALK-negative lung adenocarcinoma including PI3K/mTOR signaling (TSC1, PIK3CA, AKT2), receptor tyrosine kinase signaling (ERBB4), cell cycle regulation (CHEK2, CDC27), and DNA repair (PARP4)." (PMID 24576404, 2014). "In our previous study, we reported that 90% of 52 lung adenocarcinoma samples from East Asian never smokers harbored driver mutations in just EGFR, KRAS, HER2 and ALK genes." (PMID 24533074, 2014). "EGFR/KRAS/ALK-negative lung adenocarcinoma in never-smokers is highly heterogeneous at the somatic mutation level." (PMID 24576404, 2014). "Relationship between ALK IHC and FISH in the unselected 368 lung adenocarcinomas analysis." (PMID 24667320, 2014).